CXCR4 (C-X-C motif chemokine receptor 4)
Diseases named in the same sentence as CXCR4 in open-access papers (continued):
Sharing a sentence is not in itself a finding about the gene and the disease.
breast carcinoma (continued). "Thus CXCR4 down-regulation in breast cancer cells could decrease their metastasis." (PMID 25773070, 2015). "The adhesion between breast cancer cells and BMHC was significantly increased by SDF-1α treatment at 200 ng/ml and reduced using a blocking monoclonal antibody against CXCR4." (PMID 26231656, 2015). "For this purpose, non-permeabilized and permeabilized cells were stained for TRAIL-R2 and CXCR4, along with epidermal growth factor receptor (EGFR), frequently expressed at high levels in metastatic breast cancer cells, and TRAIL-R1." (PMID 25909161, 2015). "As expected, CXCR4 was highly expressed in leukemia cell lines (90% in CEM and 71% in MOLT-4) and in colon cancer cell line HT-29, breast cancer MCF-7 and ovarian OVCAR-4 cell lines." (PMID 26020117, 2015). "Only three disease sites had more than five studies supporting the significance of CXCR4 in impacting both PFS and OS (breast cancer, gynecologic cancer and hematological malignancy)." (PMID 25669980, 2015). "The CXCR4/CXCL12 axis has been thoroughly investigated and these two factors are upregulated in breast cancer cell lines as well as the most common sites of breast cancer metastasis." (PMID 26313265, 2015). "These evidences indicated that, in addition to CXCR4, the expression of CXCR7 and LCP1 was also in the downstream of GLI1 and GLI2 in breast cancer cells." (PMID 26413813, 2015). "miR-33b can decrease the levels of MMP-2, MMP-9, LOX, CXCR4, FN and p-FAK in breast cancer cells by regulating downstream targets." (PMID 25919570, 2015). "Although breast cancer cells also express chemokine receptors including CCR5, CCR7 and CXCR4 that enhance tumor cell invasiveness and metastasis, it is unlikely that a single treatment with chemokine antagonist can directly induce tumor cell death." (PMID 26275794, 2015). "The up-regulation of chemokine receptors CXCR4 and CXCR7 impacts on the distant metastasis and prognosis of breast cancer, though knowledge about the regulatory mechanism of their expressions is limited." (PMID 26413813, 2015). "It is also used for a variety of disorders that depend on the interplay of CXCR4 with its agonist CXCL12 (also called: SDF-1) including leukemia and breast cancer." (PMID 27429863, 2015). "The Nef-M1 peptide competes effectively with the natural ligand of CXC chemokine receptor 4 (CXCR4), stromal cell-derived factor 1-alpha, to induce apoptosis and inhibit growth in colon cancer (CRC) and breast cancer (BC)." (PMID 26318034, 2015). "The present study demonstrated that the expression of CXCR4 was higher in the MCF7-GFP-NLP cells compared with the MCF7-GFP control cells, which implied that Nlp improved the migration capacity of breast cancer cell lines through activated CXCL12 and CXCR4." (PMID 25901761, 2015). "CXCR4 is a receptor for CXCL12 chemokine, which is secreted by the common sites of breast cancer metastasis, including lymph nodes." (PMID 24709997, 2014). "Western blot analysis of low CXCR4 expressing breast cancer cell lines in vitro MDA-MB-231 and MCF-7 of whole cell extracts and tumor xenograft showed CXCR4 protein expression with tumor xenograft having higher CXCR4 expression." (PMID 25514788, 2014). "BACH1 and HMGA2 enhance the development of bone marrow metastatic breast cancer by inducing MMP1, CXCR4, and osteopontin (OPN) gene expression." (PMID 25147739, 2014). "Our previous research indicated that co-expression of CXCR4 and CXCL12 was correlated with lymph node metastasis and TNM stage of breast cancer." (PMID 24810923, 2014). "The ligand for CXCR4, CXCL12 mRNA, exhibited peak levels of expression in organs that are preferential destinations of breast cancer metastasis." (PMID 25237365, 2014). "Therefore, CXCR4 is key in the growth and proliferation of breast cancer cells, indicating that the control of its activity may significantly reduce the proliferation of breast cancer cells in vitro." (PMID 24959222, 2014).
breast carcinoma (continued). "The use of Nobiletin, a citrus bioflavonoid, has been demonstrated to downregulate both of the constitutive expressions of CXCR4 and MMP-9 in human breast cancer cells." (PMID 24971349, 2014). "We analyzed expression of CXCR4 and cyclinD1 in BCL6 expressed or knocked down breast cancer cell lines and found that expression of these genes was all up-regulated by BCL6 expression." (PMID 24917186, 2014). "Some support the role of both CXCR4 and CXCR7 in breast cancer growth, whereas another study highlights the role of CXCR7 in inhibiting invasion and metastasis of breast cancer." (PMID 24886617, 2014). "The co-expression of CXCR4 and CXCL12 which correlated with lymph node metastasis and TNM stage of breast cancer also has a reasonable reason." (PMID 24810923, 2014). "An elegant study demonstrates that the chemokine receptors CXCR4 and CCR7 are highly expressed in human breast cancer cells, malignant breast tumours and metastases." (PMID 24915301, 2014). "Previous studies have shown that CXCR4 and its chemokine ligand 12 (CXCL12) are two key factors in breast cancer metastasis." (PMID 24475985, 2014). "Thus, CXCR4 could have prognostic significance for patients with breast cancer." (PMID 24475985, 2014). "In human models, studies have suggested that CXCR4 expression could correlate with human epidermal growth factor receptor (HER)-2 expression in breast cancer patients, and could be associated with the development of lung metastases, liver metastases, or bone marrow micrometastases in breast cancer." (PMID 25237365, 2014). "The expression profiles of CXCR4, CXCR7, CXCL12, and COUP-TFI in breast cancer cells from patients exhibiting different tumor grades (82 breast tumors and control non-tumor samples) were measured using real-time PCR." (PMID 24906407, 2014). "Conversely, T140 analogs are peptidic CXCR4 antagonists, originally developed as anti-HIV agents that inhibit CXCL12-induced migration of MDA-MB-231 breast cancer cells in vitro and mitigate pulmonary metastasis in vivo." (PMID 25165728, 2014). "CXCR4 and its ligand CXCL12 play an important role in promotion of tumor growth in Ewing sarcoma and mediate metastasis in ovarian, prostate and breast cancer." (PMID 24859274, 2014). "CXCR4 stimulation by its ligand SDF-1 reduced MFE of the normal breast cells lines but increased the MFE in T47D and patient-derived breast cancer cells." (PMID 24583601, 2014). "The results of IHC revealed the membrane and cytoplasmic staining of the CXCR4 protein and the nuclear and cytoplasm staining of the CXCL12 protein in breast cancer." (PMID 24810923, 2014). "We used MDA-MB-231 cells, a highly invasive human breast cancer cell line, whose invasiveness and tumorigenicity are dependent on the expression of SDF-1α receptor, CXCR4." (PMID 24887021, 2014). "To gain a deeper insight into the role of it in breast cancer, we investigated the CXCL12 and CXCR4 expression in breast cancer cells MCF-7, MDA-MB-435s, and MDA-MB-231." (PMID 24810923, 2014). "In breast cancer, the chemotactic and invasive activity of SDF-1α/CXCR4 is mediated by both Gα13-mediated activation of RhoA and Gαi-mediated activation of Rac1 via DOCK180/ELMO, which regulate cytoskeletal remodeling." (PMID 24887021, 2014). "MCF-7 breast cancer cells overexpressing COUP-TFI and human breast tumors were used to investigate the role of COUP-TFI in the regulation of CXCL12/CXCR4 signaling axis in relation to cell growth and migration." (PMID 24906407, 2014). "We have also confirmed the increased CXCR4 expression with 3D spheroids and ERK inhibition in breast cancer cell lines MDA-MB-231 and MCF7." (PMID 25514788, 2014). "Therefore, CXCR4 could be a marker for poor prognosis and metastasis of breast cancer." (PMID 24475985, 2014). "We used combined treatment of TAM and TRAN to inhibit CXCR4 and CXCL12 protein and mRNA expression levels and determined the effects of these drugs on breast cancer metastasis." (PMID 25237365, 2014).
breast carcinoma (continued). "Double staining (staining of CD45 and another protein of interest) revealed CK19+/CD45−, HER2+/CD45−, CXCR4+/CD45− and SNAIL+/CD45− cells isolated from breast cancer patients." (PMID 24709997, 2014). "Then, we detected the mRNA and protein expression of CXCR4 and CXCL12 in breast cancer cell lines by Western blot and RT-PCR." (PMID 24810923, 2014). "Here, we report that the CXCL12/CXCR4 signaling pathway, a crucial pathway in cell growth and migration, is an endogenous target of COUP-TFI in breast cancer cells." (PMID 24906407, 2014). "The positive CXCR4 protein expression was seen in 83/182 (45.6 %) cases of breast cancer and CXCL12 positive expression in 71/182 (39.0 %) breast cancer cases." (PMID 24810923, 2014). "It has been observed that BCSCs displayed higher incidence of human bone metastasis relative to the parental breast cancer cell line, and metastatic bone tissues strongly stained for CD44, CXCR4 and osteopontin." (PMID 23301832, 2013). "CXCR4 expression is increased by HIF-1α, and a study revealed higher expression of HIF-1α in breast carcinomas of patients with bone marrow metastasis." (PMID 24376734, 2013). "It has been shown that CXCL12 binding to CXCR4 induces Akt phosphorylation and increases production of the major angiogenic factor, VEGF, in the human breast cancer cell line, MDA-MB-23." (PMID 23847541, 2013). "In this comprehensive systematic literature review and meta-analysis, we reported on expression prevalence of the hypoxia-related proteins GLUT1, CAIX, CXCR4, and IGF1R in breast cancer and carcinoma in situ, benign breast disease and normal breast tissue." (PMID 24206539, 2013). "SDF-1 can also mediate endothelial permeability via CXCR4, as for instance, SDF-1 stimulation of breast cancer cells in vitro increased their passage across the endothelial barrier." (PMID 23967403, 2013). "Thus, CXCR4 could be a novel target for breast cancer therapy." (PMID 23484027, 2013). "In breast cancer cells, inhibition of CXCR7 was shown to reduce the growth and metastasis of CXCR4-positive cells." (PMID 23865743, 2013). "Conversely, other researchers demonstrated that co-expression of both CXCR4 and CXCR7 resulted in decreased CXCL12-mediated intravasation of mammary carcinoma cells and fewer metastases of these tumors to the lungs." (PMID 23847541, 2013). "In the present study, we demonstrated that HGF-induced activation of PKCζ increases CXCR4 expression and the migratory capacity of MDA-MB-436 breast cancer cells." (PMID 22242160, 2012). "Chemokine receptors CXCR4 and CCR7 are highly expressed in human breast cancer cells, malignant breast tumours, and metastasis." (PMID 23905066, 2012). "The chemokine receptor CXCR4 and its ligand CXCL12 have been shown to mediate the metastasis of many malignant tumors including breast carcinoma." (PMID 22242160, 2012). "The interaction between the CXCR4 and the cannabinoid CB2 receptor signaling also modulates chemotaxis of CD4+ T lymphocytes as well as growth and metastasis of breast cancer." (PMID 22998838, 2012). "CXCR4 has been shown to act as a co-receptor for HIV and is highly expressed in human breast cancer cells." (PMID 22506000, 2012). "The dimeric CXCL12 activates recruitment of β-arrestin 2 to CXCR4 and chemotaxis of CXCR4-expressing breast cancer cells, whereas the monomeric CXCL12 promotes the CXCR4 signaling through Gαi and Akt." (PMID 22807925, 2012). "However, without drawing a definitive conclusion due to the need of higher numbers, the present results showing absence or low CXCR4 expression in normal and benign mammary tissues may suggest a specificity of CXCR4 expression for mammary carcinomas and metastases." (PMID 22417013, 2012). "EGFR, HER2, HER3 and membrane bound CXCR4 expression levels of M13SV1-EGFP-Neo breast epithelial cells, MDA-MB-435-Hyg breast cancer cells and M13MDA435-1 hybrid cells were comparable to previously published data." (PMID 22487193, 2012).
breast carcinoma (continued). "We had previously reported that blocking the CXCR4/CXCL12 interaction with a peptidic CXCR4 antagonist, TN14003, suppresses lung metastasis in models of breast cancer and head and neck cancer." (PMID 22485156, 2012). "Consistent with the effect of other known CXCR4 antagonists, MSX-122 blocks lung metastasis of breast cancer and SCCHN, and liver metastasis of uveal melanoma in vivo." (PMID 22485156, 2012). "CXCR4 and its cognate ligand CXCL12 have been shown to play an important role in regulating metastasis of breast cancer to specific organs." (PMID 21915267, 2011). "In this study, we examined the regulation of the CXCL12/CXCR4/CXCR7 axis and its involvement in the proliferation and survival of E2-dependent and -independent breast cancer cells." (PMID 21695171, 2011). "We observed expression of CXCR4 (90%) and CB2 (58%) in primary human tumor breast cancer samples by tissue microarray analysis." (PMID 21915267, 2011). "We have found that CXCR4 and CXCR7 in breast cancer cells can make distinct contributions to tumor malignancy." (PMID 22152016, 2011). "Primary human breast cancer cells can also respond to CXCL12 and in breast cancer patients, high levels of CXCR4 expression have been correlated with lymph node metastasis in invasive ductal carcinoma and associated with poor overall survival." (PMID 24212798, 2011). "Although CXCR4 and CB2 have previously been shown to be expressed by breast cancer tissues, this is the first report showing co-expression of these receptors on breast cancer tissues and cells." (PMID 21915267, 2011). "CXCR4 and CXCR7 are the two receptors for the chemokine CXCL12, a key mediator of the growth effect of estrogens (E2) in estrogen receptor (ER)-positive breast cancers." (PMID 21695171, 2011). "We, therefore, investigated CXCR4 expression in Treg, together with the expression of CA9 and CXCL12 in basal-like and other subtypes of breast cancers." (PMID 21521526, 2011). "We also found that both CXCR4 and CB2 receptors are expressed on various breast cancer cell lines, including the highly invasive triple negative breast cancer cell line SCP2." (PMID 21915267, 2011). "Then, a 184 bp fragment of the CXCR4 promoter, which harbored the TSS motif that contains 19 CpGs, was sequenced in breast cancer cell lines." (PMID 22220212, 2011). "We find that CXCR4 and CXCR7 play different roles in metastasis, with CXCR4 mediating breast cancer invasion and CXCR7 impairing invasion but enhancing primary tumor growth through angiogenesis." (PMID 22152016, 2011). "CXCR4/CXCL12 signaling axis has been shown to promote migration and invasion of breast cancer cells to distant sites of metastasis such as the lung, brain, bone, lymph nodes, and liver." (PMID 21915267, 2011). "Specific siRNAs directed against CXCL12, CXCR4 and CXCR7 were used to assess the importance of this axis in the basal and E2-dependent growth of breast cancer cells." (PMID 21695171, 2011). "As CXCR4 and CXCR7 have been found to play a role in breast cancer growth and metastasis, we tested the effects of CXCR4 and CXCR7 overexpression on primary tumor growth, intravasation and lung metastasis formation of MTLn3 cells." (PMID 22152016, 2011). "The CXCR4 chemokine together with its ligand, CXCL12, are involved in the mechanism of breast cancer metastasis." (PMID 22220212, 2011). "The prototype selective antagonist of CXCR4, AMD3100 (Plerixafor), was reported to inhibit apoptosis of breast cancer cells by CXCR4-tropic HIV, and other inhibitors of CXCR4 are currently in development to treat various cancers." (PMID 21179547, 2010). "It has been demonstrated that the CXCR4/CXCL12 axis likewise induces chemotaxis and breast cancer cell migration." (PMID 20181250, 2010).
breast carcinoma (continued). "Several types of cancer overexpress certain surface molecules, including HER2 receptor in breast cancer, luteinizing hormone-releasing hormone receptor in most ovarian carcinomas, and CXC chemokine receptor 4 (CXCR4) receptor in multiple tumor types." (PMID 27713313, 2010). "In this respect, a very extensive research was performed on CXCL12/CXCR4 ligand/receptor pair in breast cancer, showing high expression of CXCL12 in target metastatic organs of breast tumor cells, and the expression of CXCR4 in tumor cells." (PMID 20049170, 2010). "Three invasive MCF-7 breast cancer cell clones - MCF-7/6, MCF-7/Her2.1, and MCF-7/CXCR4 cells - were employed in these studies." (PMID 21167057, 2010). "This study aims to verify the significance of CXCR4, CCR7 and their CXCL12 and CCL21 ligands, together with EGFR in the evaluation of metastasis and the prognosis of breast cancer." (PMID 20181250, 2010). "It was observed that attenuation of CXCR4 with either the blocking mAb, MAB172 or the antagonist, AMD3100 led to statistically significant attenuation of breast cancer cell migration in response to SDF1α in MCF7 and MDA-MB-231 (data not shown) cells." (PMID 20492653, 2010). "This study investigated the expression of CXCR4, CCR7, CXCL12, CCL21, and EGFR to illustrate the role of these biomarkers in breast cancer metastasis and prognosis." (PMID 20181250, 2010). "The CXCR4/CXCL12 (SDF-1) axis was the most common interaction that has been shown to be involved in many different human malignancies, including breast cancer, ovarian cancer, and prostate cancer." (PMID 20652010, 2010). "In this study, the expression of both CXCR4 and CCR7 is combined to evaluate their contribution in the lymph node metastasis of breast cancer." (PMID 20181250, 2010). "In this study we have shown that a novel antagonist of CXCR4, a mutant form of the natural ligand, CXCL12, is capable of blocking the spontaneous metastasis of breast cancer cells from the primary tumor in an orthotopic mouse model of breast cancer." (PMID 20849618, 2010). "Exposure of two human breast cancer cell lines MDA-MB 231 and MCF7 to hypoxia led to a statistically significant increase in cell surface expression of CXCR4 by 27.5% (p < 0.05) and 67.5% (p < 0.05), respectively, when compared to cells exposed to normoxia." (PMID 20492653, 2010). "Effects of neutralizing anti-Nrp2 antibody on CXCR4 expression and chemotaxis were assessed in MDA-MB-231 breast cancer cells." (PMID 19580679, 2009). "The metastatic phenotype implies multiple changes; in particular co-expression of CXCR4, VEGF-A and MMP-9 is strongly correlated with lymph node metastasis and is a prognostic marker of the metastatic ability of primary breast cancer." (PMID 19226458, 2009). "CXCR4 is known to be upregulated in breast tumors; neutralizing the interaction of CXCL12 with CXCR4 significantly reduces breast cancer cell metastases in vivo, as does the repression of CCL5 that has anti-migratory effects." (PMID 19123925, 2009). "In the previous studies, we demonstrated that VEGF-C and cytoplasmic CXCR4 expressions were correlated with poorer patient prognosis (BMC Cancer 2008,8:340; Breast Cancer Res Treat 2005, 91:125–132)." (PMID 19580679, 2009). "We have shown previouslythat DIM lowers the levels of CXCR4 and CXCL12, a chemokine receptor and itsunique ligand required for the metastasis of breast cancer." (PMID 19325924, 2009). "Of these, only vascular endothelial growth factor (VEGF) and CXCR4, showed additive responses to TGF-β and hypoxia, suggesting limited crosstalk between TGF-β and hypoxia signaling pathways in breast cancer cells." (PMID 19727403, 2009). "We havefound that genistein downregulates CXCR4 in the ER-positive (ER+) breast cancercell line, MCF-7, the ER-negative (ER−) breast cancer cell line, MDA-MB-231,and the ER+ ovarian cancer cell line, BG-1." (PMID 19325924, 2009).